IGF1 (insulin like growth factor 1)
Diseases named in the same sentence as IGF1 in open-access papers (continued):
Sharing a sentence is not in itself a finding about the gene and the disease.
acromegaly (continued). "The recommended diagnostic test for acromegaly consists of serum IGF-1 levels measurement and, in case of elevated or equivocal IGF-1, the diagnosis must be confirmed with lack of suppression of GH to < 1 μg/L, following documented hyperglycemia during an oral glucose load." (PMID 38485706, 2024). "Notably, higher concentrations of GH and IGF-1 in acromegaly increase the risk of cardiovascular complications." (PMID 37584889, 2024). "Acromegaly is a rare chronic disease, caused by the over-secretion of growth hormone (GH), that creates a pro-inflammatory state, but the exact mechanisms by which GH or insulin-like growth factor 1 (IGF-1) act on inflammatory cells are not fully understood." (PMID 38329608, 2024). "Acromegaly is a chronic disease caused by excessive secretion of growth hormone (GH) most often from a somatotroph pituitary adenoma, with subsequently increased levels of insulin-like growth factor 1 (IGF-1)." (PMID 36525222, 2023). "Patients with uncontrolled acromegaly, a disease caused by hypersecretion of GH (and characterized by consequent increase in IGF-1 levels), exhibit baseline increases in vessel wall thickness and increased wall-to-lumen ratio in retinal arterioles compared to controls." (PMID 36755922, 2023). "Thyroid gland stiffness was increased in patients with acromegaly and associated with IGF-1 levels." (PMID 36945936, 2023). "Acromegaly is a rare, chronic, and systemic disease caused by excessive secretion of growth hormone (GH), which leads to increased circulating insulin-like growth factor 1 (IGF1)." (PMID 37373068, 2023). "Increased IGF1 and GH serum levels are the diagnostic tools for acromegaly." (PMID 38203605, 2023). "In the whole acromegaly group, the data reveal that the homozygous for risk allele carriers (rs1421085, rs9930506, rs9939609) as well as carriers of only one risk allele have lower IGF-1 concentrations." (PMID 37446150, 2023). "The clinical manifestations of acromegaly are caused by systemic effects related to the prolonged exposure to GH/IGF-1 excess (musculoskeletal, cardiovascular and metabolic comorbidities) and the local tumor extension (visual-field defects, cranial-nerve palsy and hypopituitarism)." (PMID 36525222, 2023). "Organ-specific complications of acromegaly should improve or even be prevented by normalization of the GH and IGF-1 levels, and disease control could reduce the mortality risk as for the general population." (PMID 37829686, 2023). "Mild-to-moderate cognitive impairment exhibited by patients with untreated active acromegaly may be associated with prolonged exposure to excess GH and IGF-1." (PMID 36983284, 2023). "Acromegaly is a disorder caused by the development of growth hormone (GH)-producing pituitary adenoma, resulting in increased GH and insulin-like growth factor-1 (IGF-1)." (PMID 37530996, 2023). "The current review aims to depict the prevalence of cognitive alterations in patients with acromegaly and the associated factors; particular emphasis is given to the effects of sustained GH and IGF-1 excess on the cognitive function of patients with acromegaly and its possible mechanisms." (PMID 36983284, 2023). "Acromegaly is a chronic disease caused by the increased release of growth hormone (GH) and accompanying insulin-like growth factor I (IGF-1); in most cases, this is induced by a GH-secreting pituitary adenoma and rarely results from ectopic growth-hormone-releasing hormone (GHRH) or GH secretion." (PMID 36983284, 2023). "Whether the underlying mechanism of the high prevalence of CMBs in acromegaly is a direct result of excess GH/IGF-1 dynamics or rather an indirect effect remains unclear." (PMID 36505847, 2022). "Therefore, GHRA-treated patients with acromegaly and normal peripheral IGF-1 can have peripheral GH deficiency." (PMID 35448486, 2022).
acromegaly (continued). "Pregnancy in women with acromegaly seems uneventful and safe, with a similar risk regarding the women of the same age without acromegaly, especially in patients with pre-pregnancy optimal disease control, as reflected by IGF1 levels." (PMID 36359512, 2022). "In human observational studies of conditions associated with excess GH production before or after puberty, such as gigantism or acromegaly, respectively, increased systemic levels of IGF-1 have been detected and found to be associated with an overgrowth of soft tissues." (PMID 35053340, 2022). "Next to direct GH-/IGF1-induced effects, other factors such as vitamin D deficiency, hypogonadism and aggressive replacement of hypopituitarism, especially of glucocorticoids, contribute to the skeletal fragility of patients with acromegaly." (PMID 34448099, 2022). "Stringent GH/IGF-1 hypersecretion control remains the cornerstone of acromegaly management, since smoldering disease might cause cartilage loss, and arthropathy progression." (PMID 35726113, 2022). "Acromegaly is a rare disease entity caused by benign tumors of the pituitary gland for the most part that leads to hypersecretion of growth hormone (GH) and the resultant increase in insulin-like growth factor-1 (IGF-1)." (PMID 33859902, 2021). "Acromegaly is a chronic progressive disease caused by an excess secretion of growth hormone from the pituitary adenomas and the resultant increase in an insulin-like growth factor (IGF-1)." (PMID 34912391, 2021). "Acromegaly is caused by excessive secretion of the growth hormone (GH), resulting in increased production of insulin-like growth factor-1 (IGF-1), which is responsible for clinical manifestations and for the systemic complications associated with increased mortality." (PMID 34917145, 2021). "Acromegaly is a rare disease caused by growth hormone (GH) hypersecretion mostly due to a pituitary adenoma, with consequent increase in insulin-like growth factor-1 (IGF-1) levels." (PMID 34702173, 2021). "IGF-1 level at the diagnosis time and the presence of hypertension were found to be associated with DM development in another study including Mexican patients with acromegaly." (PMID 34217172, 2021). "Acromegaly is an endocrine disease that usually originates from the somatotropic cells of the pituitary gland and causes the release of excess growth hormone (GH) and insulin-like growth factor 1 (IGF-1)." (PMID 34013701, 2021). "In patients with acromegaly, chronic excess of GH and IGF-1 secretion causes biventricular concentric hypertrophy and then interstitial fibrosis develops, which is accompanied by increased extracellular collagen deposition, lympho-mononuclear infiltrations, and myofibrillar derangement." (PMID 33992041, 2021). "There are still controversies about the duration of acromegaly and whether GH and IGF-1 are related to the increased risk of coronary heart disease." (PMID 33869029, 2021). "Acromegaly is a rare chronic disease caused by excessive production of growth hormone (GH), mostly by a pituitary adenoma, and subsequent insulin-like growth factor 1 (IGF-1) excess." (PMID 34501445, 2021). "Associated comorbidities in acromegaly patients like hypogonadism may aggravate periodontitis; thus the expected protective effects of high serum GH/IGF1 levels on periodontitis may be diminished." (PMID 33154456, 2020). "Acromegaly is a chronic endocrine disease that is mostly caused by growth hormone (GH)-secreting pituitary adenomas (PAs), resulting in excessive circulating levels of insulin-like growth factor 1 (IGF1) and in high morbidity and mortality." (PMID 33042013, 2020).
acromegaly (continued). "The potentially beneficial effects of the high sKlotho levels on endothelial function and inflammation seem to be outweighed by negative effects of hyperphosphataemia and other disturbances related to GH/IGF-1 excess, and are insufficient to reverse the increased cardiovascular risk in acromegaly." (PMID 32458292, 2020). "Acromegaly is an endocrine disorder most commonly caused by chronic excess secretion of growth hormone (GH) from a pituitary adenoma and subsequent hepatic hypersecretion of insulin-like growth factor 1 (IGF-I)." (PMID 32217809, 2020). "Increased CVD risk and mortality was observed in both IGF-1 deficiency (e.g. Growth hormone deficiency (GHD)) and IGF-1 excess (e.g. acromegaly) groups, whereas decreased mortality was found for IGF-I levels between 0 and +1 SD, which is suggested to be the optimal range in adults." (PMID 32458292, 2020). "Acromegaly is a rare disease that is characterized by uncontrolled growth hormone (GH) secretion, most commonly caused by a pituitary adenoma, which leads to excessive production of insulin-like growth factor 1 (IGF-1)." (PMID 31612224, 2020). "The inverse relation between pro-inflammatory cytokines and class 1 APP in acromegaly may be caused by effects of GH and/or IGF-1 on the interaction between cytokines and APPs." (PMID 32458292, 2020). "GH and IGF-1 increase bone turnover and acromegaly is associated with distinct alterations in bone compartments showing lower trabecular bone quantitative parameters, while cortical bone density seems better preserved and found decreased only in patients with vertebral fractures." (PMID 31417493, 2019). "Acromegaly, a condition of chronic GH and IGF-1 hypersecretion, is frequently associated to cardiovascular complications, although recent studies have shown a reduction in the prevalence of these comorbidities in well-controlled patients and a mortality risk similar to normal aging population." (PMID 31396153, 2019). "Acromegaly is a rare disorder predominantly caused by a growth hormone (GH)-secreting pituitary adenoma, consequently resulting in elevated secretion of insulin-like growth factor-1 (IGF-1)." (PMID 31939490, 2019). "The pathogenesis of colonic neoplasia in acromegaly is thought to be caused by the increased serum GH and IGF1 levels, such excess may facilitate the growth of either pre-existing colonic tumors, or initiate their development." (PMID 31293513, 2019). "GH and IGF1 excess are associated with increased mortality and morbidity, and thus, the reduction in GH and IGF1 levels is considered the main therapeutic goal in acromegaly." (PMID 30843342, 2019). "This rate of reduction in IGF-1 levels may improve associated comorbidities of patients with partial controlled acromegaly, and as a consequence enhance their quality of life." (PMID 31460622, 2019). "Our previous study found that successful surgery in patients with acromegaly could significantly reduce GH/IGF-1 expression, which was associated with disease development." (PMID 31477080, 2019). "Acromegaly is a disease that causes peculiar facial features, body types, and metabolic abnormalities due to the excessive secretion of growth hormone (GH) and insulin-like growth factor 1 (IGF-1)." (PMID 31540583, 2019). "Thus, GH and IGF-1 are thought to be associated with tumorigenesis and cancer progression in patients with acromegaly." (PMID 29593792, 2018). "High levels of GH and IGF-1 and a longer disease duration were independent risk factors for several complications in acromegaly patients, including cardiovascular disease, obstructive sleep apnea hypopnea syndrome, body composition changes, thyroid nodules and retinal choroid diseases." (PMID 30555420, 2018). "Acromegaly is a rare, chronic, life-shortening disease caused by hypersecretion of growth hormone (GH), virtually always due to a pituitary adenoma, that in turn results in elevated circulating levels of insulin-like growth factor 1 (IGF-I)." (PMID 29789410, 2018).
acromegaly (continued). "Acromegaly is also associated with “central apnea” which streams from alterations in the non-behavioral system controlling ventilation caused by the direct effects of GH/IGF-1 levels on the respiratory center." (PMID 28490347, 2017). "This could be related to disease pathophysiology since the dysregulation of glucose metabolism in CD and acromegaly could be uniquely linked to downstream effects associated with chronic exposure to elevated levels of cortisol or GH/IGF-1, respectively." (PMID 27405306, 2016). "It was developed by acromegaly experts and structured to reflect key components associated with diagnosis and the management of patients with acromegaly, namely signs and symptoms (S), associated comorbidities (A), GH levels (G), IGF-1 levels (I), and tumor profile (T)." (PMID 26377024, 2016). "Chronic exposure to elevated GH and IGF-1 levels is associated with insulin resistance, which may be counteracted by the compensatory hyperfunction of pancreatic beta cells in patients with acromegaly with normal glucose tolerance." (PMID 27405306, 2016). "Acromegaly is caused by hypersecretion of growth hormone (GH), which leads to increased levels of circulating insulin-like growth factor 1 (IGF-1), and Cushing’s disease arises from chronic hypercortisolism associated with oversecretion of adrenocorticotropic hormone (ACTH)." (PMID 27716353, 2016). "Acromegaly is a disease most often caused by benign somatotrophic pituitary adenomas that lead to elevated secretion of growth hormone (GH), which stimulates increased expression of insulin-like growth factor 1 (IGF-1)." (PMID 28025627, 2016). "Growth hormone induces the expression and secretion of IGF-1, so phenotypes associated with acromegaly may be due to either GH signaling, IGF-1 signaling or a combination of both." (PMID 26087292, 2015). "Uncontrolled acromegaly implies that persistently elevated GH and IGF-1 levels may be present in patients with a high risk of developing thyroid cancer." (PMID 25329702, 2014). "Acromegaly, an orphan disease usually caused by a benign pituitary tumour, is characterised by hyper-secretion of growth hormone (GH) and insulin-like growth factor I (IGF-1)." (PMID 19814797, 2009). "Acromegaly is a chronic endocrine disease characterized by the excessive production of growth hormone (GH), which causes an increase in plasma concentrations of insulin-like growth factor-1 (IGF-1), triggering various morphological alterations and systemic complications." (PMID 40142714, 2025). "In our case, the coexistence of acromegaly and an ancient schwannoma is intriguing; however, given the rarity of both conditions and the absence of a well-established biological mechanism linking GH/IGF-1 excess to schwannoma formation, a coincidental association cannot be excluded." (PMID 41479497, 2025). "Changes in body composition caused by IGF-1 overproduction could affect bone quality in acromegaly." (PMID 37670889, 2023). "After ruling out the causes of discrepant levels of GH and IGF-1 (such as physical exercise, pregnancy, hypothyroidism and hyperthyroidism), the patients were considered affected by active acromegaly, also in accordance with the persistence of symptoms of active acromegaly." (PMID 35922724, 2022). "Ophthalmic changes in acromegaly depend on the compression and infiltration of the pituitary somatotroph adenoma on the optic chiasm and surrounding structures (mass effect) and on the symptoms associated with the effect of GH-stimulated excess IGF-1 on the eye tissue." (PMID 36431227, 2022). "Acromegaly is a rare chronic disease caused by an excessive secretion of growth hormone (GH), mostly due to an adenoma of the anterior pituitary gland and resulting in an increased circulating concentration of insulin-like growth factor 1 (IGF-1), the main effector of GH activity." (PMID 35207363, 2022).
acromegaly (continued). "Although the underlying pathophysiology has not been fully elucidated, the spontaneous overproduction of GH and IGF-1, increasing age, prolonged duration of disease and the coexistence of other cardiovascular risk factors are crucial to cardiac complications in patients with acromegaly." (PMID 33869029, 2021). "Many studies demonstrate favorable effects of GH replacement therapy in adults with GH deficiency, and of normalization of GH and IGF-1 levels in acromegaly, on cardiovascular risk factors, but the presented data suggest that there may be an optimal target level of IGF-1." (PMID 33633687, 2020). "Acromegaly, often caused by a benign pituitary adenoma, manifests as a broad range of signs, symptoms, and comorbidities caused by the tumor (headaches and visual field defects) and by the long-term effects of GH/IGF-1 hypersecretion on multiple organs and tissues." (PMID 30269264, 2019). "Thus, it is currently considered that the biological basis for the association between colonic neoplasms and acromegaly results from the known mitogenic actions of GH/IGF1, together with slow intestinal transit in in a usually enlarged and redundant large bowel." (PMID 31293513, 2019). "The observed trend in recent years towards a general reduction in the delay in acromegaly diagnosis may play an important role in the treatment of excessive GH/IGF-1 levels and their associated comorbidities, thus reducing morbidity and mortality in acromegaly." (PMID 30269264, 2019). "Interestingly, they found an independent association between CFR and IGF-1, thus concluding that IGF-1 could have an important role in microvascular dysfunction in acromegaly that could be partially improved by disease control." (PMID 31396153, 2019). "Therefore, biochemical control of GH and IGF-1 levels may reduce the risk of colon cancer in patients with acromegaly." (PMID 28025627, 2016). "Furthermore, IGF-1 causes an increase in 1,25-dihydroxyvitamin D [1,25(OH)2D] levels by stimulating the expression and activity of the 1a-hydroxylase in the kidney, which leads to an altered calcium–phosphate balance in uncontrolled acromegaly." (PMID 26082755, 2015). "Interestingly, only a small proportion (24%) of clinicians submitting samples of cats which subsequently proved to be at high risk of having acromegaly (IGF-1 > 1000 ng/ml), reported they strongly suspected acromegaly to be present on the basis of the clinical picture." (PMID 26023776, 2015). "The relationship between the GH/IGF-1 axis and the cardiovascular system has been extensively demonstrated in numerous experimental studies and confirmed by the derangements of cardiac structure and function reported in patients with both GH excess (acromegaly) and GH deficiency (GHD)." (PMID 20676279, 2009). "Moreover, numerous trials have shown that GH suppression, associated with IGF-1 normalization, reduces cardiovascular mortality to that of general population, which supports the concept that cardiac alterations in acromegaly are strictly related to GH/IGF-1 excess." (PMID 20676279, 2009). "After fasting, GH and IGF-1 levels in acromegaly patients were unchanged, whereas healthy individuals showed increased GH and decreased IGF-1." (PMID 41472889, 2026). "The treatment of acromegaly aims to normalize GH and IGF-1 levels, manage complications, and reduce mortality." (PMID 41472889, 2026). "In the acromegaly group, the mean GH and IGF-1 are 19.5 ± 33.3 μg/L and 468.5 ± 154.8 ng/mL, respectively." (PMID 41488995, 2026). "This work aims to provide novel insights into how chronic GH/IGF‐1 excess remodels the brain network architecture, potentially uncovering biomarkers for the early detection of CNS involvement in acromegaly." (PMID 41550023, 2026). "The increased cancer risk in acromegalic patients did not correlate with age, sex, age at diagnosis, time to diagnosing acromegaly, duration of acromegaly, or GH and IGF-1 levels at diagnosis." (PMID 41753260, 2026).